NOD1 (nucleotide binding oligomerization domain containing 1)
Diseases named in the same sentence as NOD1 in open-access papers (continued):
Sharing a sentence is not in itself a finding about the gene and the disease.
infection (continued). "Wild-type and NOD1/NOD2-deficient mice were infected intravaginally with C. muridarum, and bacterial shedding was determined by swabbing at multiple time points over the course of infection." (PMID 32487756, 2020). "To address whether RIPosome formation upon Shigella infection is dependent on NOD1, we performed siRNA-mediated knockdown of NOD1 before infection." (PMID 31350258, 2019). "An OmpA-deficient strain of K. pneumoniae shows increased stimulatory activities in airway cell responses through activation of TLR2-, TLR4-, and NOD1-mediated recognition; accordingly, this mutant is completely excluded from the lung in an animal infection model." (PMID 30153274, 2018). "Indeed, 2 out of 5 WT and 3 out of 5 NOD1/2DKO mice died or were euthanized at day 2 or 3 post infection." (PMID 29211798, 2017). "Our data suggest that TIFA, NOD1, and CagA all contribute to the NF-κB-driven inflammatory response in gastric epithelial cells; however, how much each of these pathways contributes to natural infection remains an open question." (PMID 28811347, 2017). "Finally, a study demonstrated that NOD1 recognizes Clostridium difficile and regulates intestinal neutrophil recruitment, a typical local inflammatory response to infection that has been demonstrated to be defective in NOD1-deficient mice." (PMID 25071778, 2014). "Moreover, we have shown that Legionella pneumophila, an intracellular bacterium, recruits neutrophils to the site of infection in a Nod1- and Nod2-dependent manner." (PMID 25084278, 2014). "Therefore, we evaluated the role of NOD1 stimulation during in vitro infections with Mtb, one of the most successful intracellular pathogens." (PMID 25253572, 2014). "In every cell line, IL-8 induction is a very early event upon infection, which is maximal during the 2 to 4 hours in the presence of the bacteria and independent of CagA, likely involving H. pylori PG recognition by NOD1." (PMID 23565224, 2013). "This feature accounts for NOD1-dependent responses that generate resistance against infection." (PMID 23162548, 2012). "However, NOD1 levels were decreased in response to P. gingivalis with an initial decrease in protein levels and a partial recovery later in the infection." (PMID 22685397, 2012). "However, at later stages of infection, both Nod1−/− and Nod2−/− mice produced significantly increased levels of proinflammatory cytokines in the lungs." (PMID 23162548, 2012). "Therefore, the detailed mechanism by which NOD1 confers resistance to infection with T. cruzi remains to be described and a possible cross-talk between NLR and TLR pathways during infection with T. cruzi waits for further investigation." (PMID 22496959, 2012). "As suggested by previous transcriptional profiling experiments, we confirmed that Myd88−/−and Rip2−/−macrophages, which are defective in TLR and Nod1/Nod2 signaling, respectively, strongly upregulated Il23a and Gem following infection with wildtype L. pneumophila." (PMID 21390206, 2011). "These authors imply that NOD1 induction of hBD2 upon infection with cag-PAI-positive H. pylori may be mediated by NF-κB activation, but this is unclear since NF-κB activation is assessed by reporter gene assays that may not reflect endogenous NF-κB regulation." (PMID 21152124, 2010). "Nod1 was shown to play a role in C. pneumoniae-mediated activation of human endothelial cells in vitro, But it is unclear which Nod receptors detect C. pneumoniae in macrophages and during in vivo infection." (PMID 19360122, 2009). "The observation that NOD1 was involved in infection with H. pylori and Listeria monocytogenes further strengthened the hypothesis that NOD proteins act as important cytosolic PRRs." (PMID 16827942, 2006).
infection (continued). "Nucleotide-binding oligomerization domain-containing protein 1 gene (NOD1) mediates innate and acquired immunity by activating the NF-κB signal pathway and promoting the expression of inflammatory cytokines to induce the resistance against the infection of bacteria." (PMID 33672418, 2021). "In the context of resectional surgery for cancer, an understanding of how NOD1 may participate in the inflammation and infection mediated metastasis can ultimately provide new insights for managing malignancies with a curative intent and optimizing clinical outcome." (PMID 31956962, 2020). "In this context, the remaining levels of produced chemokines and recruited neutrophils in MyD88-deficient mice could result in the activation of Nod1 and Nod2, which was not enough to control the infection and resolve the septic episode." (PMID 25084278, 2014). "The human cytosolic Pattern Recognition Receptors, Nod1 and Nod2, sensing bacterial cell wall fragments, recognize intracellular C. pneumoniae and subsequently mediate activation of the transcription factor NFkB which plays a key role in regulating the immune response to infection." (PMID 24616885, 2014). "Indeed, activation of NOD1 occurred upon infection of epithelial cells by Helicobacter pylori." (PMID 17397264, 2007). "Once produced, IL-37 attenuated TLR2, TLR4 and NOD1-mediated activation and TLR-mediated IL-8 responses to H. pylori infection." (PMID 41689434, 2026). "Antiviral activity of NOD1 and NOD2 agonists was evaluated in an SARS-CoV-2 in vitro model of infection using lung epithelial A549-Dual cells and Vero E6." (PMID 38791357, 2024). "First, NOD1 agonist TriDAP reduced the SARS-CoV-2-GFP+ cells by 49% (p < 0.01), whilst dual NOD1/2 ligand M-TriDAP reached up to 57% of infection inhibition (p < 0.01), compared to the untreated control." (PMID 38791357, 2024). "The ability of NOD1 and NOD2 to respond to ER stress further underscores the importance of NOD1 and NOD2 during infection control and the connection between ER stress and PRR responses to manage infections." (PMID 34748367, 2022). "As NOD1 and NOD2 agonists are not released from the surface of L. interrogans due to the action of LipL21, L. interrogans is able to also escape recognition by NOD1 and NOD2 to establish an infection in the host." (PMID 35967403, 2022). "NOD1 also interacts with the cofilin phosphatase SSH1, that regulates the actin severing activity of cofilin, which contributes to NOD1 activation upon infection with S. flexneri." (PMID 35967403, 2022). "Compared with the control group, S. Infantis elevated the expression of NOD1, NOD2, and RIP2 at 5 h post-infection." (PMID 36142312, 2022). "This strain had lost the ability to generate a γH2AX-signal upon infection of AGS cells, consistent with the interpretation that NOD1 is required to drive this signalling." (PMID 35505004, 2022). "Then, we performed qPCR to further evaluate the expression of NOD1 in the liver samples of Z8-R, Z8-S and SZ7-S flocks after infection with DHAV-3." (PMID 34745142, 2021). "In the context of infection, the B. abortus T4SS effector virB-coregulated effector C (VceC) induces ER stress through interaction with the chaperon BiP and triggers NOD1/2- and RIP2-dependent IL6 production." (PMID 34201509, 2021). "Common PRRs of NOD1, NOD2, NLRP3, NLRC4, NLRC5, and AIM2 were detected using qPCR assays after 90 min of infection with A. sobria at a MOI of 10 and 2 h gentamycin treatment followed by 12 h incubation." (PMID 34513725, 2021). "A priori upregulation of both NOD1 and RIPK2 in MAP-infected macrophages would suggest an efficient host control over the intracellular infection." (PMID 31969876, 2019). "NOD1 is constitutively expressed in intestinal epithelial cells, while NOD2 is upregulated by treatment with specific pro-inflammatory cytokines or by infection with invasive bacteria." (PMID 29616010, 2018).
infection (continued). "infection, heightened levels of G-CSF led to a reduction in CXCL12 expression in the BM via Toll-like receptor and NOD1/2 signaling." (PMID 30619317, 2018). "Both Nod1 and Nod2 have been shown to recruit ATG16L1 at early stages of infection by S. flexneri to initiate autophagosome formation." (PMID 29875765, 2018). "We have also shown that in mice NOD1 is a potent PRR in the kidney, actively participating in the control of experimental infection with uropathogenic E. coli through neutrophil recruitment." (PMID 29211798, 2017). "Future studies will focus on the mechanism by which NOD1 transactivates MHC class I and II related genes, and the effect of the correlation between NOD1 and CD44 signaling in pathogen infection." (PMID 28592872, 2017). "Future studies will focus on assessing NOD1 and TIFA innate immune signaling pathways in primary gastric organoids and animal models of infection to further elucidate their respective contributions to H. pylori detection." (PMID 28811347, 2017). "Therefore, NOD1 polymorphisms may not be related directly to the onset of CD, but through a complicated mechanism that is triggered by infection." (PMID 27069792, 2016). "These authors observed, through the use of Nod1-/- and Nod2-/- mice, that IL-12 and TNF-α levels were reduced after infection." (PMID 24155744, 2013). "The same group further demonstrated that NOD1 and NOD2 were crucial for the induction of mucosal Th17 responses during the early stages of infection with Citrobacter rodentium and S. enterica Typhimurium." (PMID 23162548, 2012). "Taken together, this study demonstrates that NOD1, NOD2 and Rip2 are dispensable for the control of B. abortus during in vivo infection." (PMID 22203860, 2012). "Infection with Wuhan, Alpha, Beta, Delta or MA10 resulted in the activation of the host pattern recognition receptors such as Toll-Like Receptors (TLRs), C-type Lectin Receptors (CLRs), and NOD1/2 receptors as early as 3 dpi." (PMID 40416961, 2025). "However, during infection with certain strains of SVCV, NOD1 appears to play a dichotomous role by augmenting the binding between dsRNA and MDA5a." (PMID 39878363, 2025). "Similarly, in mrigal, the expression levels of NOD1 and NOD2 in the gills, liver, kidney, and intestine significantly increased after infection with either S.agalactiae or Aeromonas hydrophila." (PMID 40218399, 2025). "In human hepatocytes, NOD1 expression significantly increases following infection; however, NOD2 levels are not significantly impacted." (PMID 39878363, 2025). "This study revealed that the expression of NOD1 and RIPK2 is upregulated in BV2 cells and mouse brain tissues during PRV infection, which may be influenced by other signalling pathways after infection, and further research is needed." (PMID 39696641, 2024). "Infection with Japanese encephalitis virus (JEV) greatly elevated the transcriptional and protein expression of NOD1 in mice, and knockout of NOD1 enhanced resistance to JEV infection by inhibiting the neuroinflammatory response and multiple downstream signaling pathways." (PMID 36920176, 2023). "Furthermore, NOD1 and NOD2 play a role in stimulating Th1 cell responses required for parasitic clearance in mouse models of infection with Toxoplasma gondii, Trypanosoma cruzi, and Leishmania infantum." (PMID 37006312, 2023). "Even in the absence of infection, chemically induced ER stress promotes IRE1α activation of NOD1/2 signaling and inflammation." (PMID 34748367, 2022). "We now show that IRE1α-NOD1/2 also has a role in inflammation and clearance in C. rodentium infection, which also may play a role in EHEC/EPEC human infections." (PMID 34748367, 2022). "Furthermore, we examined NOD1 and RIPK2 expression at different infection time points in cultured U251 cells and observed that JEV infection upregulated their expression in a time-dependent manner, as determined by qRT-PCR and immunoblot analysis." (PMID 35638852, 2022).
infection (continued). "For example, heat-iMVA infection triggered higher levels of IFN-inducible genes than MVA, including Ifih1 (MDA5), Ddx58 (RIG-1), Oasl2, Oas3, TLR3, Nod1, Ifna4, Ifnb1, Ccl5, Cxcl9, Cxcl10, and members of the guanylate binding protein (Gbp) family, as largely dependent on STING (marked as b)." (PMID 36261460, 2022). "Notably, the NOD-like receptor proteins NOD1 and NOD2 can participate in innate immune responses, and NOD1 stimulates the release of chemokines, such as CXCL-8, CXCL-1, and CXCL-2, which can attract neutrophils to the site of infection." (PMID 35993024, 2022). "Notably, NOD1 and NOD2 have been detected in the plasma membrane at the infection sites and upon activation by peptidoglycans both NOD1 and NOD2 induce the phosphorylation of their common adaptor receptor-interacting protein kinase 2 (RIP2)." (PMID 35846362, 2022). "Understanding the nuances of the roles NOD1 and NOD2 play in metabolism may be essential for effective therapies for these prevalent metabolic diseases, chronic inflammatory diseases, or infection." (PMID 33503814, 2021). "Moreover, it has been demonstrated that palmitoylation of NOD1 and NOD2 is essential for their activation and localisation to the plasma or endosomal membrane during detection of PG or bacteria during infection." (PMID 33498269, 2021). "We speculate that NOD1 might have replaced the function of NOD2 and played a role in infection in poultry." (PMID 34745142, 2021). "As expected, NOD1 knockdown reduced IL-8 secretion upon infection but did not affect IL-8 secretion induced by autoactivation due to overexpression of RIPK2, compared with control siRNA-treated cells." (PMID 31350258, 2019). "The lack of difference in bacterial loads between WT and NOD1/2DKO mice upon infection with a virulent strain of L. interrogans strain L495 drove us to study the potentially atypical composition of leptospiral PG." (PMID 29211798, 2017). "This response, which is independent of NOD1, drives robust NF-κB-dependent inflammation within hours of infection and precedes NOD1 activation." (PMID 28811347, 2017). "Surprisingly, NOD1 KO attenuated but did not abolish IL-8 production in response to infection with wild-type H. pylori, suggesting that an additional host pathway(s) is activated by bacterial factors delivered through the cag-T4SS." (PMID 28811347, 2017). "In contrast, HBD3 expression is NOD1-independent but relied on epidermal growth factor receptor (EGFR)-mediated ERK activation, suggesting distinct temporal functions for the two antimicrobial peptides during infection." (PMID 28272373, 2017). "Moreover, the infection of NOD1 humanized mice with M58 and the C5M58 complemented strain resulted in a lower bacterial load observed for M58 compared to C5M58 at 48h and 72h post infection." (PMID 29211798, 2017). "Since NF-κB was not activated after a single infection, it showed that Nod1-Rip2 pathway, not TLR-MyD88 or TLR-Trif3 pathways, is responsible for NF-κB activation." (PMID 28300841, 2017). "The gene products of NOD1 and NOD2 are key cellular receptors that recognize intracellular pathogens and have been shown to be important in the recognition of MAP in epithelial cells early in infection." (PMID 27093613, 2016). "NOD1 not only activates NF-κB, but also MAPK JNK as seen in infection with Shigella flexneri." (PMID 25722880, 2015). "In Caco-2 cells, NOD1 prevents IκB kinase and NF-κB activation in response to EIEC infection." (PMID 25915861, 2015). "In contrast to our findings related to NOD2, our data indicated that uninfected brain tissues express little or no NOD1, and only a modest level of expression was detectable following infection with the gram-positive bacteria S. pneumoniae." (PMID 25443778, 2014). "A possible role for cytosolic signaling is not without precedent as NOD1/2 sensing of peptidoglycan can upregulate miR-155 during infection with other organisms." (PMID 25295729, 2014).
infection (continued). "Certain instances result in upregulation of Nod2 in the presence of Plasmodium sporozoites, while in other cases Nod1 and Nod2 confer changes in cytokines but do not promote survival after infection." (PMID 24155744, 2013). "In a different study, NOD1 and NOD2 had redundant roles in the protection against C. rodentium infection and mediated IL-6-dependent IL-17 production in the cecum at early time point (1–4 days after infection)." (PMID 24381573, 2013). "As T. cruzi parasites lack peptidoglycan or any known agonist for NOD1, it would be interesting to determine whether NOD1 directly senses a T. cruzi-derived PAMP, or if the NOD1 pathway is indirectly activated during infection." (PMID 22496959, 2012). "In this regard, Silva and coworkers (2010) recently demonstrated that the effective response required for host resistance to infection was exclusively mediated by NOD1 but not by NOD2 receptor." (PMID 21869919, 2012). "BMDMs from Nod1−/− mice showed impaired induction of NF-κB-dependent products in response to infection and failed to restrict T. cruzi infection in the presence of IFN-γ." (PMID 23162548, 2012). "In addition, these finding were supported by studies showing that infection with H. pylori induced IL-8 production by the gastric epithelial cell line, AGS cells, in an NOD1/cag-PAI-dependent manner." (PMID 21152124, 2010). "Therefore, it is likely that NOD1-mediated type I IFN production and ISGF3 activation provide protective Th1 responses upon infection with cag-PAI-positive H. pylori." (PMID 21152124, 2010). "Additionally, when macrophages are tolerized by LPS, the role of NOD1 and NOD2 in cytosolic surveillance becomes more critical during infection." (PMID 18769721, 2008). "Previous observations showed that infection with a low dose of L. pneumophila allowed for the detection of T4SS-dependent NF-κB activation in macrophages lacking either MyD88 or Nod1." (PMID 19043549, 2008). "The common pathways upregulated upon infection by each of these three viruses included innate antiviral and inflammatory pathways, such as OAS and ISG15-mediated antiviral responses, interferon α/β signaling, cytokine and interleukin signaling, NOD1/2 signaling, and the NLRP3 inflammasome pathway." (PMID 40857262, 2025). "Here, we identified that NOD1 silencing reversed the upregulation of KLF5 expression caused by P. gingivalis, which indicated that NOD1 played a non-negligible role in response to P. gingivalis-infection." (PMID 40016182, 2025). "Further evaluation demonstrated that innate immune induction specifically by NOD1 agonists also blocked SARS-CoV2 in vitro infection without a broad activation of inflammatory signaling in myeloid cells, suggesting the use of NOD1 agonists as a putative novel antiviral strategy against SARS-CoV-2." (PMID 38791357, 2024). "However, less is known about the mechanism of recognition of parasitic infection: whether NOD1 and/or NOD2 directly recognize PAMPs from the parasites, or if the infection is recognized indirectly." (PMID 37006312, 2023). "The expression of the tlr2, tlr9, nod1 and nod2 receptors in the gills did not change significantly after bacterial exposure when compared to controls (0 h), although a tendency to decreased tlr2 expression was seen at 6 and 24 h post-infection." (PMID 37731496, 2023). "Therefore, BMVs are a mechanism used by bacteria, irrespective of their mode of infection, to deliver their PG-cargo to the cytosol, resulting in the activation of NOD1 and subsequently a proinflammatory response." (PMID 33498269, 2021). "In fish, NOD1 can also respond to infection of Gram-negative bacteria and may play an important role in the identification of bacterial components." (PMID 30013548, 2018).